IL6 (interleukin 6)
Diseases named in the same sentence as IL6 in open-access papers (continued):
Sharing a sentence is not in itself a finding about the gene and the disease.
breast cancer (continued). "Circulating levels of FABP4 are markedly increased in obese individuals due to release from an expanded adipose tissue depot and FABP4 can induce mammary tumor stem cells by enhancing ALDH1 activity via IL-6/STAT3 signaling." (PMID 33339340, 2020). "In breast cancer, MDSCs were shown to enhance the stem-like qualities of tumor cells by secretion of IL-6 and nitric oxide (NO) in a STAT3-dependent manner." (PMID 32117287, 2020). "We indeed observed that CAF modulate BCL-2 dependence in luminal breast cancer cells via IL-6 signaling, shifting from a BCL-2 to a MCL-1 survival dependence." (PMID 32722518, 2020). "In this study, we fabricated a microfluidic chip replicating the blood and lymph vessel channels in the human body and monitored the effects of inflammatory cytokine, IL-6, on breast cancer metastasis process at the in vitro condition." (PMID 33659239, 2020). "Breast cancer cells exposed to the pro-inflammatory IL-6 cytokine exhibited enhanced invasion capacity and increased drug resistance; also, inflammatory microenvironments are known to expand the CSC pool and increase tumor initiation." (PMID 32478091, 2020). "The expression of IL-6 was reportedly decreased by treadmill running in a breast cancer mouse model." (PMID 32309219, 2020). "In breast cancer, exosome containing miR-140 or IL-6 from preadipocytes promotes breast cancer progression." (PMID 32971847, 2020). "On the other hand, ZEB1 contributes to the formation of the tumor microenvironment by regulating the levels of various inflammatory cytokines, such as interleukin 6/8 (IL-6/8), which resulted in increased tumor growth in basal-like breast cancer cells." (PMID 32014049, 2020). "In breast cancer patients, crosstalk between microbes, systemic IL-6, and neutrophils has been observed." (PMID 32354130, 2020). "IL-6 levels were significantly increased in the breast cancer group (BC: 3.91 ± 0.83) compared to the normal mouse group (CTL: 1.00 ± 0.63, P = 0.010)." (PMID 32309219, 2020). "IL-6 expression in gastric or breast cancer cells strongly enhanced tumor infiltration of TWIST1-expressing cancer-associated fibroblasts." (PMID 32565805, 2020). "Mechanistically, overexpression of linc00514 stimulated IL-6 and IL-4 secretion of breast cancer cells via STAT3/Jagged1 axis, and promoted monocyte polarization into M2-like macrophages and increase the tumor progression." (PMID 32943090, 2020). "A robust surrogate marker of aggressive breast cancer phenotype via regulation of EMT is interleukin-6 (IL-6)." (PMID 33335078, 2020). "In the stroma of breast cancer, adipocytes, along with fibroblasts, macrophages, and cancer cells produce adipokines such as leptin, adiponectin, autotoxin, and IL-6." (PMID 32033341, 2020). "In this study, we used IL-6 to change the properties of various breast cancer cells from those of epithelial cells to mesenchymal cells." (PMID 33659239, 2020). "RB depletion in breast cancer cells increased production of multiple cytokines and chemokines, including IL-6 and CCL2." (PMID 32244804, 2020). "As knocking down DANCR inhibited EMT and stemness of malignant breast cancer cells, we examined the effect of shDANCR on the production of IL‐6 and TGF‐β from these cells." (PMID 31860165, 2020). "IL-6 regulates insulin, resistin and estrogen, and thereby directly affects breast cancer development." (PMID 32824813, 2020). "The IL-6 exposure to different subtypes of breast cancer cells was induced epithelial-mesenchymal transition (EMT) and improved tissue invasion property (8-fold)." (PMID 33659239, 2020). "Clinical trials are ongoing for investigating utilization of HER2 therapies in combination with IL-6 therapies to overcome drug resistance in HER2-positive breast cancer." (PMID 33123472, 2020).
breast cancer (continued). "In breast cancer, CAFs have been shown to act in a paracrine manner through secretion of inflammatory modulators such as IL-6, inducing Notch activation in cancer cells and thus promoting the stem cell phenotype and resistance." (PMID 32575680, 2020). "Overexpression of YB-1 in breast cancer induces IL-6 secretion, in turn, treatment with IL-6 increases YB-1 expression, both of which upregulate EMT." (PMID 33123472, 2020). "Here, we find that PAK4 phosphorylates RUNX1, which upregulates downstream genes related to osteoclast differentiation and maturation, including Jagged-1,IL-1α,IL-1β,IL-6 and PTHrP in breast cancer cells." (PMID 32549768, 2020). "First of all MCF-7 breast cancer cells were treated with IL-6 which is an established promoter of breast cancer progression and its inhibition leads to the induction of apoptosis." (PMID 32922496, 2020). "The interaction of leptin with cytokines can also influence breast cancer progression: leptin acts on both tumour cells and tumour stroma to secrete inflammatory cytokines such as IL-1, IL-6, TNF-α, and growth factors." (PMID 32033341, 2020). "IL-6 level is also higher in radiotherapy-treated breast cancer patient’s plasma compared to unexposed patients." (PMID 31963587, 2020). "In breast cancer cells, activation of IL-6/IL-6R signalling suppressed MAOA expression in hypoxic environment." (PMID 32273550, 2020). "We found that the control and IL-6-treated breast cancer cells exhibited different degrees of invasiveness through the lymphatic, layered-hydrogel in the presence of FBS as a chemoattractant." (PMID 33659239, 2020). "Metformin disrupts tumor-stromal crosstalk by inactivating CAF and preventing their subsequent secretion of pro-tumoral factors such as SDF-1 and IL-8 in breast cancer or IL-6 in ovarian cancer." (PMID 33080792, 2020). "The results show that long-term exercise reduces IL-6 mRNA expression in breast cancer mice, and long-term running can inhibit IL-6 in the liver." (PMID 32309219, 2020). "Exosomal miR-25-3p released from hypoxic breast cancer cells stimulated migration and proliferation of tumor cells by inducing IL-6 secretion and activating NF-κB signaling in macrophages." (PMID 32503591, 2020). "Mechanistically, a subsequent study found that autophagy supports the survival of breast cancer stem cells by mediating the secretion of interleukin-6 (IL6), a cytokine that is important for breast cancer stem cell maintenance." (PMID 32195258, 2020). "Species richness, as well as fat mass, positively correlated with critical cytokine IL6, suggesting that the gut microbial population is altered in the obese state, which can lead to chronic inflammation, which can worsen breast cancer outcomes." (PMID 32354130, 2020). "For example, administration of IL-6 or IL-8 is sufficient to induce mammosphere-forming activity in luminal-type breast cancer cells." (PMID 32244804, 2020). "In a study of breast cancer T47D cells, IL-6 promotes EMT through the increased activation of ERK1/2 and the phosphorylation of Shp2, a protein tyrosine phosphatase." (PMID 33123472, 2020). "More specifically, IL-6 and IL-1α cytokines are known to enhance the promotion of tumor growth, angiogenesis, and metastasis of aggressive human cancers such as breast cancer." (PMID 32526880, 2020). "In studying the relationship between STAT3 and CSCs, Polyak and colleagues found that the IL-6/JAK2/Stat3 pathway is preferentially active in CD44+CD24− stem-enriched breast cancer cells, where it is required for their growth." (PMID 32391382, 2020). "In order to investigate how exercise in breast cancer affects inflammatory cytokines, IL-6, IL-18, TNF-α, and CRP mRNA expression levels were analyzed in the livers of the study mice." (PMID 32309219, 2020). "For example, Ixabepilone, which was associated with CD40, CXCR4, IL6, and SERPINE1, were used in locally advanced breast cancer and metastatic breast cancer, can potentially be repurposed to treat OCSCs." (PMID 32977853, 2020).
breast cancer (continued). "In the context of the gp130 cytokines, IL-6 has been reported by numerous groups to play a role in breast cancer progression, and these effects correspond to hormone receptor expression." (PMID 32023849, 2020). "Breast cancer cells that migrate to bones express cytokines and growth factors such as interleukin (IL)-6, IL-8, IL-11, tumor growth factor (TGF)-β, prostaglandin E, or PTHrP, which can mediate RANKL expression." (PMID 32117996, 2020). "So far IL-2, IFNα, IFNβ and occasionally IFNγ, IL-6, IL-12 have been the cytokines used for anti-tumor treatment of advanced breast cancer either to induce or increase hormone sensitivity and/or to stimulate cellular immunity." (PMID 32887217, 2020). "Variants in patients with breast cancer have also been correlated with body mass index, waist to hip ratio, and expression of COX-2, IL-6, and Cyp19A1 in breast adipose tissue." (PMID 32708725, 2020). "For example, an in vitro study of drug-sensitive and drug-insensitive breast cancer cell lines showed that IL-6 was present at a high concentration in the media of drug-insensitive cells, but absent in the media of drug-sensitive cells." (PMID 33597950, 2020). "In breast cancer, IL-6 and IL-8 are increased in resistant cells compared to parental cells sensitive to tamoxifen." (PMID 32499779, 2020). "Dysfunctional VAT secretes pro-inflammatory cytokines such as tumor necrosis factor-alpha (TNF-α) and interleukin-6 (IL-6), thereby stimulating aromatase activity, which eventually drives higher estrogen production to support luminal type breast cancer growth." (PMID 31992764, 2020). "Resistin and IL-6 expression is also positively correlated with serum levels in breast cancer patients." (PMID 32824813, 2020). "Breast cancers disrupt the balance between osteogenesis and osteolysis by releasing factors such as PTHrP, IL-6, MMPs that leading to bone destruction." (PMID 32549768, 2020). "A number of studies have reported the elevated expression of IL-6 in AA breast cancer patients compared to CA patients." (PMID 32824813, 2020). "Our data suggest that PAA is useful for breast cancer treatment and the Stat3/IL-6 signal as a marker for CSCs targeting." (PMID 33202749, 2020). "Elevation of IL-6 in the tumor microenvironment has been demonstrated in various types of cancers such as breast cancer." (PMID 32922496, 2020). "Some cytokines (IL-1, IL-6, IL-11) stimulate while others (IL-12, IL-18, IFNs) inhibit breast cancer proliferation and/or invasion." (PMID 32887217, 2020). "Another TME component is MSC which protect ovarian cancer cells from carboplatin-induced apoptosis through inhibition of caspase activation, however, secrete high levels of IL-6 and IL-8 contributing to chemoresistance in breast cancer." (PMID 32499779, 2020). "Activation of an inflammatory NF-kB/IL6/STAT3 signaling pathway generates cancer stem cells in breast cancer cells in vitro and is also implicated in colon and other cancers." (PMID 32399610, 2020). "The expression of IL-6 can also be driven by IL27-p28 (IL-30), which has tumor-promoting effects in prostate cancer and in breast cancer is enriched for and associated with the TNBC subtype." (PMID 32023849, 2020). "A recent study demonstrated that race affects inflammatory cytokine levels (IL-6 and IFN-γ) and breast cancer risk." (PMID 32714862, 2020). "When adipocytes are cocultured with breast cancer cells, adipocytes increase secretion of IL-6, which in turn promotes invasion and migration of tumor cells." (PMID 33339340, 2020). "Many groups since the 1980s have demonstrated that recombinant IL-6 slows proliferation of breast cancer cells in 2D cultures, with most of these studies focusing on ER+ human breast cancer cell lines like MCF7, T47D, and ZR-75-1 cells." (PMID 32023849, 2020). "Subsequently, the IL-6-treated breast cancer cells were injected along with IL-6-containing media into the LTB chip, and the injected cells were monitored using a confocal microscope." (PMID 33659239, 2020).
breast cancer (continued). "The effects of inflammatory cytokine interleukin 6 (IL-6) on the migration of breast cancer cell lines were abolished in the presence of kinase inhibitors, although this interleukin does not activate RET directly." (PMID 32993133, 2020). "For example, in an in vitro model of breast cancer, the IL-6/Stat3 axis has been shown to be critical in the conversion of non-CSC into CSC." (PMID 32478091, 2020). "Previous articles have evidenced the elevation of IL-6 in the tumor microenvironment, in several types of cancers including breast cancer." (PMID 33680016, 2020). "Every subtype of the IL-6-treated breast cancer cell except the S-HBCC was significantly (P-value < 0.01) more invasive and attained over a 5-fold increase compared to the control cells (SK-BR-3: 8-fold; MCF 7: 4.97-fold; and MDA-MB-231: 4.35-fold)." (PMID 33659239, 2020). "Reports indicate that elevated levels of plasma IL-6 and CRP are associated with reduced progression free and overall survival in patients with breast cancer who were treated with anti-PD-L1 immunotherapy." (PMID 33123173, 2020). "The implication of cancer cells in ATR knockdown in CAFs has been proven in vitro by showing that breast cancer cells downregulate ATR in breast fibroblasts in an IL-6/STAT3-dependent manner and via AUF-1." (PMID 32414408, 2020). "Previous researches have reported that exogenous and endogenous IL-6 can promote breast cancer invasion and migration through the activation of EMT." (PMID 33123472, 2020). "We have recently shown that breast cancer cells activate breast stromal fibroblasts (BSFs) in an IL-6-dependent manner." (PMID 32414408, 2020). "Immunoblotting as well as quantitative RT-PCR were utilized to show the role of breast cancer cells and IL-6 as well as AUF-1 in downregulating ATR in breast stromal fibroblasts." (PMID 32414408, 2020). "We believed that the induction of M2 polarization of macrophages is related to the activation of Jagged1-mediated Notch signaling pathway and the increased secretions of IL-4 and IL-6 in breast cancer cells." (PMID 32943090, 2020). "After the generation of two endothelial cell layers with the hydrogel, the IL-6-treated breast cancer cells were injected into the lymphatic channel to emulate the cancer metastasis process in the microfluidic system." (PMID 33659239, 2020). "AA and CA breast cancer patients have resistin and IL-6 as the most differentially-expressed cytokines, with a relatively higher level of expression in AA patients." (PMID 32824813, 2020). "Meanwhile, we found that the siRNA-mediated JAG1 knockdown impairs the secretion and expression of IL-4 and IL-6 of breast cancer cells." (PMID 32943090, 2020). "Since IL-6 exerts its influence on breast cancer cells via JAK2/STAT3 pathway, the inhibitory effect of Nar-Cpm combination on IL-6 influence further proves its ability to target JAK2/STAT3 signaling pathway." (PMID 33680016, 2020). "In contrast to ER+ breast cancer, both HER2+ and TNBC have elevated levels of IL-6, causing an autocrine feedback loop through IL-6-activated STAT3." (PMID 32023849, 2020). "In contrast, the treatment of breast cancer cells with recombinant IL-6 diminished mitochondrial superoxide production, which was associated with increased mammosphere-forming activity and hormone-independent growth." (PMID 32244804, 2020). "Recently, we reported that tubulosine inhibited JAK2/STAT3 signalling in IL‐6‐induced breast cancer." (PMID 32558259, 2020). "IL-6 knockout mice and IL-6 overexpression mice showed a decreased numbers of intestinal polyps in knockout mice and increased intestinal polyps in overexpressed mice, in a breast cancer mouse model." (PMID 32309219, 2020). "Specifically, the concentrations of IL6 and TNFα were higher in women with breast cancer with pooled mean difference of 2.15 (95% CI 1.64–2.66) and 1.70 (95% CI 1.10–2.30), respectively." (PMID 33004039, 2020).
breast cancer (continued). "The IL-6-treated breast cancer cells successfully immobilized and colonized on the HLEC layer and began invading into the inner side of the hydrogel layer." (PMID 33659239, 2020). "IL6 promotes the mobility and tumorigenesis of normal and breast cancer epithelial cells through a NOTCH dependent pathway." (PMID 32399610, 2020). "In vivo experiments revealed that injection of breast cancer cells with the miR-25-3p inhibitor substantially reduced the tumor size by inhibiting IL-6-mediated STAT3 activation." (PMID 32503591, 2020). "Our results confirm those of a previous report demonstrating elevated levels of TNF-α and IL-6 in sera of patients diagnosed with advanced breast cancer and high load of metastases." (PMID 32306920, 2020). "Blockade of IL-6 effect by an IL-6 antagonist, tocilizumab, reduces the breast cancer stem cell population, resulting in decreased cancer growth and metastasis in mice." (PMID 33123472, 2020). "In basal like breast cancer cells, serum response factor (SRF) interacts with YAP and induces IL-6 expression, which promotes stemness of basal like breast cancer cells." (PMID 32596154, 2020). "The exposure of breast cancer cells to IL-6 induced dramatic morphological changes in the cells, from the epithelial to the mesenchymal structure." (PMID 33659239, 2020). "ANGPTL2 and IL-6 enhance the reaction of breast cancer cells to bone-derived CXCL12 through the upregulation of CXCL12 receptor CXCR4 in these cancer cells, respectively." (PMID 33123472, 2020). "While we have not evaluated mechanism in our study, previous studies have demonstrated cytokines IL-6 and IL-8 that are produced by aggressive tumor types, including breast carcinomas, can act as chemoattractants to efficiently recruit CTCs 27, 58-60." (PMID 32685030, 2020). "Previous studies showed that IL6 inhibits proliferation and increases cell migration in the T47D breast carcinoma cell line." (PMID 33374146, 2020). "The cytokine profiles of canine malignant and metastatic mammary carcinomas were described, illustrating the upregulation of IL-1, IL-6, TNF-α, and IFN-α expression." (PMID 32225066, 2020). "In basal-like breast carcinomas, autocrine IL-6 sustains Notch-mediated promotion of proliferative self-renewal and increased invasiveness." (PMID 33279931, 2020). "Accordingly, our findings revealed an association between cats with mammary carcinoma and higher serum levels of two pro-inflammatory cytokines (TNF-α and IL-6), positively correlated with serum CTLA-4 levels, as reported in humans and mice." (PMID 32123292, 2020). "The serum CTLA-4, TNF-α and IL-6 levels of 57 female cats with mammary carcinoma were determined by ELISA, and immunohistochemistry was performed to evaluate CTLA-4 and FoxP3 expression in tumor cells and interstitial lymphocytes." (PMID 32123292, 2020). "Breast cancer-derived EV have been demonstrated to induce an IL-6-mediated pathway via gp130/STAT3 signaling, leading to TAM polarization." (PMID 32878277, 2020). "Using the Curtis TCGA data set, we find that high expression of OSM correlates with decreased breast cancer patient survival, similar to previous studies with IL-6." (PMID 31007849, 2019). "Adipocytes induce epithelial mesenchymal transition of breast cancer cells through paracrine IL-6/Stat3 signalling." (PMID 31383893, 2019). "IL-1β induces IL-6 production in breast cancer cells, as well as additional cytokines and growth factors including TGF-β, TNF-α, and EGF." (PMID 31231372, 2019). "We discussed the correlation of PAK1/IL-6 and Stat3/IL-6 in breast cancer patient from the publicly available dataset such as TCGA (The cancer genome atlas)." (PMID 31658701, 2019). "To investigate the direct recruitment of Stat3 to the promoter region of the IL-6 gene in breast cancer cells, we performed EMSA and ChIP assays." (PMID 31658701, 2019).